IL6 (interleukin 6)
Diseases named in the same sentence as IL6 in open-access papers (continued):
Sharing a sentence is not in itself a finding about the gene and the disease.
liver fibrosis (continued). "IPA of MYOC/CCL19 fibroblast gene expression correlating with the mRSS revealed several prominent pathways: senescence, hepatic fibrosis signaling, IL-6 signaling, STAT3 signaling, TGF-β signaling, protein ubiquitination, JAK/Stat signaling, and role of JAK1, JAK2 and TYK2 in interferon signaling." (PMID 35943798, 2022). "The mRNA levels of liver fibrosis markers (Acta2, Col1a1, Col3a1, and Timp1), cholangiocyte proliferation markers (Krt7 and Krt19), inflammation markers (Il6 and Il1b), and the progenitor cell marker (Sox9) were markedly decreased in miR-200c-BDL mice compared to con-BDL mice." (PMID 34880414, 2022). "Interestingly, interferon gamma (IFN-γ) increased but TNF-α, interleukin 6 (IL-6), hepatic fibrosis, and steatosis decreased in the add-on groups." (PMID 35889747, 2022). "During liver fibrosis, HSCs are a cellular source of IL-6, which may might partly contribute to the elevation of α-SMA and type I and III collagens in HBV-positive sera and/or CsTP-treated LX-2 cells." (PMID 36510325, 2022). "Liver injury may retain the active surface of HSCs and accelerate the migration of inflammatory cells to the injured liver, secreting a significant number of inflammatory mediators such as TNF-α, IL-6, and IL-1β to enhance the development of liver fibrosis." (PMID 36017390, 2022). "IL-4 and IL-6 have shown a potent protective effect on liver fibrosis." (PMID 36544761, 2022). "Then, module analysis of the 113 key OGEs was performed using MCODE and the CytoNCA plugin to obtain 6 core genes (CXCL8, MAPK1, AKT1, SRC, VEGFA, and IL-6), which might play important roles in the effects of JQH against WD-associated liver fibrosis." (PMID 35707473, 2022). "ALDH2 deficiency accentuated CCl4-induced hepatic fibrosis via ROS overproduction, while ALDH2−/− mice were prone to get liver inflammation and fibrosis through malondialdehyde-acetaldehyde induced paracrine IL-6 activation in Kupffer cells." (PMID 35864505, 2022). "Further studies showed that BM-MSCs could play a protective role in liver fibrosis treatment by affecting the IL-6/STAT-3 signaling pathway and downregulating IL-17A." (PMID 35895169, 2022). "Meanwhile, the postoperatively changed cytokines after splenectomy, including decreased TGF-β1 and elevated IL-6 produced in splenic tissue, may also contribute to the favorable effect on liver fibrosis." (PMID 33573590, 2021). "Similarly, in CCl4-induced liver fibrosis levels of hepatic Il6 and Tgfβ gene expression were markedly lower in IL-37tg mice." (PMID 33746950, 2021). "IL-6 also plays a dual-functional role in the process of liver fibrosis-induced inflammation." (PMID 34801005, 2021). "The mechanism of how IL-6 prevents and reverses hepatic fibrosis is still under investigations." (PMID 34047814, 2021). "However, it was also demonstrated that non-parenchymal cells recruited via IL-17 are important sources of IL-6 during liver regeneration and hepatic fibrosis." (PMID 34047814, 2021). "Proinflammtory cytokines, such as IL-6 play an important role in liver fibrosis." (PMID 33809062, 2021). "Similarly, knock down of Jun N-terminal kinase 12 (JNK-1/2) from KCs reversed liver fibrosis in a choline-deficient L-aminoacid-defined (CDAA) model, with a decline in inflammatory responses, including TNF-α, IL6, IL-1β, and TGF-β." (PMID 32612603, 2020). "In the in vivo model, infusion of the miR-150 secretome into mice with liver fibrosis abrogated the increase in serum levels of systemic inflammatory cytokines, such as IL-6 and TNF-α, and induced increased expression of antifibrotic, proliferation, and antioxidant activity markers in the liver." (PMID 32152450, 2020). "Moreover, based on measurement of the collagen area, Ishak fibrosis score, MDA levels, IL-1, and IL-6, the therapeutic effect of hBM-MSCs-Ex against liver fibrosis was significantly greater than that of hBM-MSCs." (PMID 30885249, 2019).
liver fibrosis (continued). "Therefore, serum TNF-α and IL-6 play an important role in the development of TAA-induced hepatic fibrosis." (PMID 31362375, 2019). "Importantly, IL-6 (interleukin 6) has also been shown to contribute to the initiation of hepatic fibrosis." (PMID 31885614, 2019). "Preoperative serum inflammatory mediators (such as IL6, IL8, and TNF-α) may be associated with liver fibrosis and cirrhosis." (PMID 31781194, 2019). "Thus, we suggest that BM-MSCs ameliorate liver fibrosis via downregulation of IL17A dependent IL-6/STAT3 signaling pathway." (PMID 30346985, 2018). "Hence, IL17 is associated with IL6 concentration and serum level of IL6 and IL17 evaluate the severity of liver fibrosis." (PMID 30346985, 2018). "Recently, the therapeutic potential of IL-6 was shown by its ability to reverse liver fibrosis." (PMID 29610679, 2018). "In the present study, we evaluated the capacity of the BM-MSCs in the modulation of cytokines milieu and signal transducers, based on unique inflammatory genes Il17a and Il17f and their receptors Il17rc and their effect on the IL6/STAT3 pathway in CCl4-induced liver fibrosis in rats." (PMID 30346985, 2018). "Collectively, we suggest that BM-MSCs might play an immunomodulatory role in the treatment of liver fibrosis through downregulation of IL17A affecting IL6/STAT3 signaling pathway." (PMID 30346985, 2018). "Moreover, expression of Th1 or Th2 cytokines important for liver fibrosis, such as IL-6, IL-10, IL-13, and TNF-α, were also detected in our experiment." (PMID 29703259, 2018). "However, the role of IL-6 in liver fibrosis induction is still under debate, with most studies referring to pathological changes that occur in the liver after the in-vivo induction of hepatic fibrosis." (PMID 28472150, 2017). "To elucidate whether IL-10 and IL-6 are involved in the suppressing effect of EXE on hepatic fibrosis, we detected their serum levels in the control group and EXE-treated group." (PMID 29464186, 2017). "Both IL-17a and IL-6 have been correlated with severe liver conditions, such as liver fibrosis, which may contribute to MHE34." (PMID 26757951, 2016). "Transforming growth factor (TGF)-β1 and interleukin (IL)-6 are pro-fibrotic cytokines that are upregulated during chronic liver inflammation and their serum and tissue concentrations correlate positively with the degree of liver fibrosis." (PMID 27681697, 2016). "The expression of chitinase 3-like 1 by hepatic stellate cells, which was positively associated with cell survival and negatively with liver fibrosis, might be enhanced by MSC-derived IL-6." (PMID 27409608, 2016). "After menopause women change from an estrogen protective milieu, where HCV-mediated inflammation is controlled, to a hepatic proinflammatory state where estrogen levels drop and IL-6 and TNF-α cytokines levels greatly increase possibly increasing the risk of hepatic fibrosis progression." (PMID 26090666, 2015). "Elevated levels of TNF-α, IL-6, and IL-1 β were also previously reported in liver fibrosis in rats." (PMID 25945106, 2015). "BBG also ameliorated liver fibrosis and down-regulated hepatic interleukin-6 (IL-6), tumor necrosis factor-alpha (TNF-α), PDGF, IL-1β, transforming growth factor-beta (TGF-β), p-extracellular-signal-regulated kinases (ERK), and alpha-smooth muscle actin (α-SMA) expressions in CBDL rats." (PMID 25933224, 2015). "Given that elevated inflammation due to TNF-α, IL-6 and IL-1β are amongst the causative factors of liver fibrosis and liver steatosis, and high levels of TNF-α, IL-6 and IL-1β are known to deregulate glucose metabolism, we measured the levels of these cytokines in the liver." (PMID 24260182, 2013). "Increased MSC survival within fibrotic liver pretreated with IL-6 leads to functional hepatic improvement and may be a novel therapeutic strategy for the treatment of liver fibrosis." (PMID 23531302, 2013).
liver fibrosis (continued). "Indeed, a positive correlation between IL-6 expression in hepatocytes and the severity of hepatic fibrosis in patients with non-alcoholic fatty liver disease (NAFLD) was observed." (PMID 23840852, 2013). "Collectively, these findings underscore the importance of understanding IL-6’s tissue-specific roles and suggest that while IL-6R antagonists hold promises for modulating immune-driven fibrotic pathways, their translation into therapies for liver fibrosis must be approached with caution." (PMID 40693271, 2025). "Additionally, cytokines such as TGF-β, IL-6, and Interleukin-8 (IL-8) are significantly elevated in the perihepatic sinusoidal wall and interlobular septa of the liver, correlating with the degree of inflammation and liver fibrosis." (PMID 39995661, 2025). "Interestingly, at 24 weeks of age, our analysis of IL-6 abundance revealed additive effects in DualExp offspring, aligning with the increased hepatic fibrosis, steatosis, and ALT and AST release, which also exceeded those caused by either maternal or paternal alcohol use alone." (PMID 39908263, 2025). "Nevertheless, further studies are required to reveal whether the sustained increase of Fendrr contributes to the pathogenesis of liver fibrosis by inducing proliferation of hepatocyte and creating a regenerative niche, other than promoting the secretion of IL-6." (PMID 38762176, 2024). "However, a careful analysis, considering the clinical subtypes of the disease, indicated that IL-6 concentrations were not significantly linked to steatohepatitis and liver fibrosis." (PMID 38732626, 2024). "In this case, we would expect an increase in IL-6 levels that could indicate a chronic inflammatory response that would contribute to lung and liver damage and could be involved in the development of liver fibrosis observed in some patients." (PMID 39334730, 2024). "The qPCR results showed that overexpression of miR-552-3p significantly reduced the mRNA levels of fibrotic genes (Col1a1, Col3a1, Timp-2) and inflammatory genes (Il-6, Ccl2, F4/80) in mice livers, which demonstrated that miR-552-3p could reduce liver fibrosis and inflammation in mice again." (PMID 37496991, 2023). "In addition, IL-1β and IL-6 promote hepatocyte injury and liver fibrosis." (PMID 37958712, 2023). "Similarly, our results showed that TFPCP could ameliorate the inflammatory response (TNF-α, Il-6 and IL-1β) in a CCl4-induced liver fibrosis rat model." (PMID 38074148, 2023). "CCl4 treatment could up‐regulate the pro‐inflammatory cytokines TNF‐α, IL‐6 and IL‐1β in the liver, and MulA treatment significantly reduced the levels of these cytokines, indicating that MulA might alleviate liver fibrosis via inhibiting inflammatory cytokines secretion." (PMID 37324833, 2023). "Furthermore, oxidative stress can, directly and indirectly, contribute to the up-regulation of the nuclear factor kappa-light-chain-enhancer of activated B cells (NF-kB) and pro-inflammatory cytokines (TNF-α, IL-6, and IL-1) that are involved in the apoptosis and development of hepatic fibrosis." (PMID 37242133, 2023). "IL-6 may be a helpful prognostic marker for liver fibrosis among individuals with HIV infection." (PMID 36405584, 2022). "However data regarding the role of IL-6 in liver fibrosis are contradictory, depending probably on homeostasis between inhibitory and stimulatory signals during the different stages of liver fibrosis and under the effect of different etiologies of liver fibrosis." (PMID 36544761, 2022). "Some researchers proposed that this elevated interleukin-6, which is partly secreted by activated macrophages induced during liver fibrosis, might induce inflammatory response proteins in the hepatocytes (such as CRP (C-reactive protein), ferritin, complement, and clotting factors)." (PMID 35369116, 2022).
liver fibrosis (continued). "The role of IL-6 in the pathogenesis of NAFLD has been controversial; some evidence suggests that IL-6 could promote hepatocyte proliferation and have a protective role in liver fibrosis, while other observations point to a positive correlation between IL-6 and NAFLD severity." (PMID 34025683, 2021). "In addition, the Ingenuity Pathway Analysis predicted the impact on tryptophan, isoleucine, and valine pathways, hematopoiesis from pluripotent stem cells, hepatic fibrosis, retinoid X receptor activation, endocytosis, and the complement system by IL-6/IL-6R treatment." (PMID 34795667, 2021). "Consistently, aggravated liver fibrosis development in TcrbKO mice was confirmed by elevated fibrogenic gene expression (Sma, Col1, Tgfb), along with abnormal intrahepatic immune status (including alleviated levels of Il2, Il6, Il23, Ifng, and enhanced levels of Il17 and Tnfa)." (PMID 33391261, 2020). "In addition, BAR502 reduced liver fibrosis scores by 70% and expression of pro-fibrogenetic genes (αSMA and α1-collagen), as well as the inflammatory score and liver expression of F4/80, IL-1β, IL-6, MCP-1, RANTES and TNFα mRNA." (PMID 28202906, 2017). "The marked upregulation of hepatic TNFA and IL6 at the time of early menopause, becoming non-significant in late menopause, could explain the strong but selective association we observed between liver fibrosis and early menopause." (PMID 26183212, 2015). "Therefore, TNF-α and IL-6 secretion inhibition was considered to be able to reduce liver fibrosis." (PMID 23843869, 2013). "However, the prolonged IL-6 expression and MDSCs accumulation in the liver may have negative effect in promoting liver disease progression such as liver fibrosis and HCC development." (PMID 21394214, 2011). "Recently, we reported that KD feeding for 14 weeks at TN induced liver fibrosis and MASH in C57BL/6 mice through liver IL-6-JNK signaling." (PMID 40864559, 2025). "Network pharmacology identified IL-1β, IL-6, and TNF-α as potential targets for YQHX in treating liver fibrosis.The UPLC detected multiple potential active components." (PMID 41296792, 2025). "Recent research shows that Fendrr, a long non-coding RNA, binds to STAT2 to enhance IL-6 expression, stimulating HSC via paracrine signaling and promoting liver fibrosis progression." (PMID 40969371, 2025). "Studies suggest that in liver fibrosis, QR significantly reduces the expression of pro-inflammatory cytokines, including TNF-α and IL-6." (PMID 40076811, 2025). "Our results showed that MIF was important for the synthesis of the proinflammatory cytokines IL-6 and TNF in the myocardium in a model of TAA-induced liver fibrosis." (PMID 41020850, 2025). "The serum aminotransferase (ALT and AST), alkaline phosphatase (ALP), bilirubin (TBIL and DBIL), bile acid, inflammatory cytokines (IL-6, IL-1β, TNF-α) and liver fibrosis indicator (HA, LN, PC-III and IV-C) concentrations were measured by ELISA kits." (PMID 41293246, 2025). "High IL-1β/IL-6 and NLRP3 levels drive liver fibrosis in experimental models of non-alcoholic fatty liver disease (NAFLD) mice." (PMID 40332584, 2025). "In the MASH model, LGG primarily exerted its effects by inhibiting the TGF-β/SMAD signaling pathway and reducing the expression of pro-inflammatory factors (e.g., IL-1β, IL-6, TNF-α), thereby mitigating liver fibrosis and inflammation." (PMID 40778202, 2025). "Excessive ROS can further aggravate liver fibrosis by activating NF-κB, promoting the release of inflammatory cytokines, such as TNF-α and interleukin-6 (IL-6)." (PMID 39689154, 2025). "Our findings suggest that TNF, IL-6, PPARG, and MMP9 are potential therapeutic targets that influence liver fibrosis progression by regulating inflammatory responses and apoptosis through multiple pathways." (PMID 39869574, 2025).
liver fibrosis (continued). "In this context, the secretion of IL-6 enhances the expression of GP73, which, in turn, contributes to the inflammatory pathway activating the HSC and leading to the development of liver fibrosis." (PMID 40075792, 2025). "By blocking the NF-κB signaling pathway, liver tissue can exhibit reduced expression of proinflammatory cytokines (IL-6 and TNF-α), in addition to decreased collagen deposition, fibrosis marker α-SMA expression, and liver fibrosis." (PMID 40552161, 2025). "The main indicators for evaluating the degree of hepatic fibrosis include HA, LN, Collagen I, Collagen III, PCIII, PIIINP, IV-C, IL-6, and TNF-α, α-SMA, HYP, PDGF-BB, CTGF and TGF-β1." (PMID 38781262, 2024). "Consistent with animal experiments, hepatic fibrosis markers (α-SMA, collagen I, and CTGF) and inflammatory markers (IL-1β, IL-6, and TNF-α) were significantly decreased in activated LX-2 cells after PFD and/or AGP treatment." (PMID 38946862, 2024). "Studies have reported that Liuweiwuling tablets can alleviate bile-duct ligation-induced liver fibrosis mainly by inhibiting the expression of the inflammatory cytokines IL-1β1, TNF-α, and IL-6." (PMID 38195573, 2024). "For instance, reduced inflammation (IL-6, MAPK, NF-κB) and liver fibrosis in CCl4-treated rats was observed due to SM (50 mg/kg BW for 10 weeks) treatment." (PMID 38247522, 2024). "Based on the results, VSC-CDs in various dosage groups significantly diminish the levels of TNF-α, IL-6, and IL-1β, signifying that VSC-CDs inhibit the inflammatory response and thereby alleviate liver fibrosis." (PMID 38116381, 2023). "The potential application of mLO(-DAPT/D3) for the modeling of liver fibrosis was then examined after sustained exposure to a fibrosis-inducing cytokine cocktail (FIC, a mixture of TGFβ1, TNFα, IL-6, and IL-1β)." (PMID 36737811, 2023). "Triggering IL6/STAT3 signaling enhances HSC activation and liver fibrosis, while IFNγ/STAT1 signaling exhibits opposite effects." (PMID 37860111, 2023). "As inflammation is one of the major etiological agents leading to liver fibrosis, we detected the severity of inflammation using measurements of TNF-α protein expression level and TGF-β and IL-6 gene expression levels." (PMID 36978885, 2023). "Meanwhile, TGF-β can synergize with IL-6, TNF-α, or IL-1β to accelerate the development of hepatic fibrosis." (PMID 38074148, 2023). "In the present study, the productions of IL-6, TNF-α and IL-4 were significantly elevated in C. sinensis-induced liver fibrosis, which is consistent with previous studies." (PMID 36693049, 2023). "Pro-inflammatory factors such as tumoral necrosis-alpha factor (TNF-α), interleukin-1β (IL-1β), interleukin-6 (IL-6), and the transformant growth factor β1 (TGF-β1) contribute to liver fibrosis induced by oxidative stress." (PMID 38001866, 2023). "CTGF expression and production were increased upon treatment with TGF-β1, FFA or IL-6, suggesting a role of CTGF in ECM deposition during the development of liver fibrosis." (PMID 36672237, 2023). "Administration of AAV8-PGC-1α or TSA to increase PGC-1α mitigated the I/R-promoted M2-type macrophage polarization by inhibiting the IL-6/STAT3 signaling, and alleviating liver fibrosis in I/R mice." (PMID 37679346, 2023). "IL-6, TNF-α and IL-4 are important cytokines involved in liver inflammation, liver injury and liver fibrosis." (PMID 36693049, 2023). "IL-6, TNF-α, MCP1, and IL-1β are the inflammatory cytokines responsible for NASH progression, which play an important role in hepatic fibrosis." (PMID 37762300, 2023). "Taken together, TLR3 inhibit IL-6 and TNF production via p38/ERK signaling pathway, a phenomenon that resulted in the alleviation of C. sinensis-induced liver fibrosis." (PMID 37167198, 2023). "It has been reported that IL-6 and CXCL8 levels are related to the degree of liver fibrosis and can promote the process of liver fibrosis by inducing HSCs activation and regulating apoptosis." (PMID 35707473, 2022).